APOA1 (apolipoprotein A1)
Diseases named in the same sentence as APOA1 in open-access papers (continued):
Sharing a sentence is not in itself a finding about the gene and the disease.
hematological cancer (1 paper, 2020). "The fact that low HDL cholesterol and apolipoprotein A1 were associated with increased risk of hematological cancers suggests that HDL particles may be essential in the tight control of proliferation and homeostasis of the hematopoietic system, perhaps hindering malignant transformation." (PMID 32998735, 2020). "The interplay between HDL cholesterol and apolipoprotein A1 with receptors responsible for cholesterol transport such as ATP-binding cassette transporters and scavenger receptors in the development of hematological cancers could be explored in future studies." (PMID 32998735, 2020).
APOA1 also shares sentences with these, for which no sentence is quoted: acute myocardial infarction (21 papers); Impaired glucose tolerance (10); angina (9); end-stage renal disease (7); systemic amyloidosis (7); viral infections (7); nephrotic syndrome (6); esophageal squamous cell carcinoma (5); hyperhomocysteinemia (5); liver failure (5); renal failure (5); small cell lung carcinoma (5); systemic inflammatory response syndrome (5); benign tumors (4); dengue (4); dialysis (4); essential hypertension (4); gastric adenocarcinoma (4); genetic disorders (4); influenza (4); lymphoma (4); osteoarthritis (4); pancreatic ductal adenocarcinoma (4); antiphospholipid syndrome (3); atopic asthma (3); bladder transitional cell carcinoma (3); cerebral infarction (3); cholangiocarcinoma (3); digestive diseases (3); focal segmental glomerulosclerosis (3).
A further 248 diseases each share a sentence with APOA1 in 3 papers or fewer.